INS (insulin)
Diseases named in the same sentence as INS in open-access papers (continued):
Sharing a sentence is not in itself a finding about the gene and the disease.
Insulin resistance (continued). "Untargeted biochemical profiling to identify biomarkers of insulin resistance following the development of targeted assays and validation of the targeted assays in a clinical cohort resulted in the development of a diagnostic that monitors insulin sensitivity status in humans." (PMID 25133529, 2014). "However, phosphorylation of IRS-1 at Ser 307 also inhibits the interaction between the phosphotyrosine binding domain of IRS-1 with the phosphorylated NPEY motif in the activated IR, disrupting insulin signaling, and may ultimately cause insulin resistance." (PMID 24918297, 2014). "Furthermore, some studies have shown that even a subtle increase in plasma TSH levels within the physiological range may affect insulin secretion and may be associated with insulin resistance and metabolic syndrome." (PMID 25364704, 2014). "In a previous study, we discovered that Res could improve insulin sensitivity and ameliorate insulin resistance in KKAy mice, which may be associated with the up-regulation of Sirt1 protein in the liver and soleus muscles and, consequently, Sirt1 and AMPK activation." (PMID 25140191, 2014). "In contrast, however, the inhibition of DGAT1 activities in the skeletal muscle or macrophage may cause insulin resistance, leading to aggravation of metabolic disorders, as a result of inhibited conversion of fatty acids substrates which induce insulin resistance into the form of triglyceride." (PMID 25405858, 2014). "Furthermore, insulin therapy may cause weight increases, hypoglycemia and iatrogenic hyperinsulinemia, which can increase insulin resistance and the potential risks of vascular disease." (PMID 25187822, 2014). "Thus, the overload of iron may be influenced by hepatic uptake and utilization of insulin, which may cause insulin resistance, further confirming that iron proteins may cause or exacerbate insulin resistance." (PMID 24926364, 2014). "Furthermore, some studies have suggested that zinc supplementation may improve insulin sensitivity and that zinc status affects some risk factors related to insulin resistance." (PMID 24416185, 2014). "The exciting observation that insulin and insulin-like growth factor (IGF) 1 signaling also triggers distinct changes in lncRNA expression [e.g., of the lncRNA CRNDE] points to the fact that lncRNAs may also be implicated in the metabolic effects of insulin and the development of insulin resistance." (PMID 24723937, 2014). "However, it is still unknown whether continuous exposure to excess exogenous insulin similar to that observed in subjects with insulin resistance and hyperinsulinemia can cause T2DM in normal mice fed on a chow diet." (PMID 24741073, 2014). "Moreover, evidence from several cross-sectional studies also indicated that high serum 25-hydroxyvitamin D [25-(OH)D] concentration may be associated with lower risk of insulin resistance, high level of insulin secretion, and lower risk of type 2 diabetes." (PMID 24868538, 2014). "Thus, insulin signalling requires ROS to be effective and it seems paradoxical that evidence points to elevated ROS as a primary cause of decreased insulin signalling and insulin resistance." (PMID 24672550, 2014). "In light of the evidence that high CLAt10,c12 intake can potentially cause insulin resistance, we endeavored to determine whether there is a health risk related to changes in glucose tolerance and insulin response as a result of increased CLAt10,c12 content in dairy products." (PMID 24956949, 2014). "The abnormal high concentration of serum lipid in diabetic mainly due to increased mobilization of free fatty acids from peripheral fat depots, since insulin inhibits the hormone sensitive lipase, insulin deficiency, or insulin resistance may be responsible for dislipidemia." (PMID 25121104, 2014).
Insulin resistance (continued). "Especially, chronic elevation in plasma free fatty acids (FFAs) levels is commonly associated with impaired insulin-mediated glucose uptake in skeletal muscles although the precise mechanism by which FFAs are involved in the development of muscle insulin resistance remains unknown yet." (PMID 24521082, 2014). "The markers of endothelial dysfunction, including soluble E-selectin (sE-selectin), are related to insulin resistance, which is associated with metabolic inflexibility, i.e., impaired stimulation of carbohydrate oxidation and impaired inhibition of lipid oxidation by insulin." (PMID 23934358, 2014). "Insulin resistance (IR) can be considered as a clinical state of low insulin sensitivity at one or more of the sites involving glucose metabolism in which a normal or elevated insulin level will cause an attenuated biologic response like insulin-stimulated glucose disposal." (PMID 24523637, 2014). "FGF21 may have a potential role as a therapeutic agent for conditions associated with insulin resistance as it has been shown that administration of a recombinant form of this hormone in obese mice and diabetic monkeys improves insulin sensitivity, body weight, and lipid profile." (PMID 23999826, 2013). "Insulin resistance and related traits are likely to be caused by abnormalities in the genes encoding for proteins involved in the composite network of insulin-signaling; in this review we have focused our attention on genetic variants of insulin-signaling inhibitor molecules." (PMID 23762820, 2013). "In the LIPGENE-SU.VI.MAX study GG homozygotes of rs3790433 SNP at the LEPR gene had increased MetS risk compared with the minor A allele carriers (OR 1.65), which may be accounted for by their increased risk of elevated insulin concentrations and insulin resistance." (PMID 23306188, 2013). "However, the function of apelin in hepatic insulin resistance, a vital part of insulin resistance, and its underlying mechanisms still remains unclear." (PMID 23437347, 2013). "Insulin depletion and elevation in glucagon levels in a Type II diabetes condition have been closely linked with dysfunction in the α-pancreatic cells, contributing (along with the more commonly implicated culprit, insulin resistance) to the development of the disease." (PMID 24324517, 2013). "Therefore, it is of great interest to investigate whether reduction in adiposity is associated with improvement in insulin secretion as well as insulin resistance." (PMID 23483954, 2013). "Higher NEFA may cause peripheral insulin resistance by interfering with the access of insulin to skeletal muscle or interfering with insulin signaling resulting in reduced glucose transport into muscle; in the liver, high levels lead to excessive endogenous glucose production." (PMID 23806173, 2013). "Finally it is possible that the inflammatory responses of which CRP is a marker induce changes in conventional risk factors such as lipids, insulin and blood sugar which are related to insulin resistance as part of the metabolic syndrome and that it is these which result in the adverse consequences." (PMID 23391158, 2013). "Moreover, reduced insulin-induced activation of Akt is a hallmark of insulin resistance." (PMID 24252636, 2013). "Given that the loss of body weight in obese individuals can improve insulin sensitivity, the effect of GL extracts on significantly reduced body weights may also contributes to its activity in the improvement of insulin resistance in the skeletal muscles of SHRSP/ZF rats." (PMID 23452929, 2013). "Furthermore, we examined whether basal insulin and insulin resistance are important risk factors of incident MetS in each gender." (PMID 24086723, 2013).
Insulin resistance (continued). "Therefore in our present study, we determined the effect of Gelam honey extract and quercetin on the stress-activated NF-κB, MAPK pathways and IRS-1 serine phosphorylation causing insulin resistance and the Akt-activated insulin signaling pathway, causing increase in insulin content." (PMID 24324490, 2013). "Thus, lowering Nlrp3 inflammasome activation may protect against the transition from insulin-resistance to an overt type 2 diabetic stage by mechanisms that involve protection from loss of insulin-producing beta cells." (PMID 23483669, 2013). "In addition, as cortisol was shown to be associated with insulin resistance, this study might suggest that the enhanced insulin sensitivity in the offspring might be facilitated by the lower cortisol levels." (PMID 22348049, 2012). "Moreover, chronically elevated levels of serum glucose predispose patients to insulin resistance and elevated serum insulin, which may exert their own effects on tumor progression." (PMID 23050155, 2012). "Furthermore, also it has been reported that conditions that modify insulin concentration during fetal life could alter the normal development of endocrine system, predisposing to insulin resistance in adult life." (PMID 22770114, 2012). "Although peripheral insulin resistance is a hallmark of the development of T2D, more recent evidence has shown that insulin resistance also exists in central nervous system (CNS), and that central insulin action plays an important role in regulating whole body glucose metabolism." (PMID 22675349, 2012). "Importantly, insulin resistance in muscle might occur at a late point in the insulin signaling cascade and be associated with IMCL and NAFLD severity." (PMID 22359625, 2012). "NAFL favors insulin resistance and high insulin plasma levels could cause Foxa1 down-regulation." (PMID 22238690, 2012). "For example, adipose tissue insulin resistance in rats fed with a glutamine-supplemented diet is accompanied by reduced TNFα and interleukin-6 levels, as well as augmented adiponectin levels, which seem to be the cause of increased insulin sensitivity in other organs." (PMID 23024762, 2012). "Moreover, insulin resistance is associated with conditions other than T2D, such as obesity, cancer, and cardiovascular disease, and therefore new insulin-sensitizing agents could potentially have extensive clinical indications." (PMID 22745632, 2012). "In contrast, despite their initial hypothesis of fetal programming of type 2 diabetes being associated with impaired insulin secretion, Hales and Barker and colleagues were the first to document the association between low birthweight and insulin resistance in humans." (PMID 22643933, 2012). "Indeed, the activation of IKKβ/NF-κB in hepatocytes-induced liver inflammation and insulin resistance and was associated with a reduced ability of insulin to suppress neoglucogenesis and with an increased production of VLDL leading to the development of hypertriglyceridemia." (PMID 23316186, 2012). "The association of IL-6 and insulin resistance seems complex, and evidence suggests that IL-6 might act at multiple levels, both centrally and on peripheral tissues, to influence body weight, energy homeostasis, and insulin sensitivity." (PMID 22804097, 2012). "Thus, although an association between NAFLD and insulin resistance is well accepted it still remains unclear whether insulin resistance causes NAFLD or hepatic steatosis per se reduces insulin sensitivity." (PMID 22393439, 2012). "Moreover, adverse effects of TFA intake on insulin sensitivity may be greater in individuals more predisposed to insulin resistance." (PMID 24278690, 2012). "While the impact of these SNVs may be masked in lean individuals, once validated in mechanistic studies, these mutations could be included in a metric used by clinicians to council at-risk children on their increased risk for insulin resistance before they become overweight and insulin-insensitive." (PMID 23396303, 2012).
Insulin resistance (continued). "Furthermore, we previously screened exons 3 and 4 including exon-intron boundaries among obese children and adolescents and identified intronic variants in intron 4, only about 7 kb away from rs17818902, that caused increased fasting serum insulin levels and increased degree of insulin resistance." (PMID 21637715, 2011). "Insulin resistance in muscle is caused by several mechanisms including fatty acid oxidation defects due to effects on mitochondrial biogenesis, oxidative stress, accumulation of lipid intermediates in muscle, and effects of pro-inflammatory cytokine on insulin signaling." (PMID 22035457, 2011). "Nonalcoholic fatty liver disease (NAFLD) and insulin resistance have recently been found to be associated with increased plasma concentrations of apolipoprotein CIII (APOC3) in humans carrying single nucleotide polymorphisms within the insulin response element of the APOC3 gene." (PMID 21793029, 2011). "However, the more marked inhibition of AS160 phosphorylation observed with CM-PA reveals an amplification of insulin resistance and may be the direct cause of the impaired insulin-stimulated GLUT4 translocation and glucose uptake." (PMID 22046423, 2011). "However, subsequent studies revealed that older rats actually show an increased rate of both glucose oxidation and insulin secretion, suggesting that this is a potential mechanism by which beta cells attempt to overcome age-associated peripheral insulin resistance." (PMID 21765202, 2011). "DBT improves insulin sensitivity through increased post-receptor insulin signaling mediated by enhancements in insulin receptor substrate-1-associated phosphatidylinositol 3-kinase step and glucose transporter subtype 4 translocation in soleus muscles of animals exhibiting insulin resistance." (PMID 19233878, 2011). "The pathophysiological mechanisms of insulin resistance are possibly secondary to a relative prolonged nutritional deficiency in the fetus, during which time the fetal metabolism constantly readjusts to slow growth with relative resistance to insulin, IGF-1, and GH." (PMID 21771322, 2011). "In addition to higher insulin responses, insulin resistance may also cause elevated postprandial levels of TGs as observed in our study." (PMID 21904606, 2011). "Inhibition of IL-6 signalling improves insulin sensitivity in humans with immunological disease suggesting that elevated IL-6 levels in type 2 diabetic subjects might be causally involved in the pathogenesis of insulin resistance." (PMID 21179199, 2010). "The association found between sCML and the homeostasis model assessment (HOMA an instrument to measure insulin sensitivity) levels of normal persons could be linked to metabolic processes, which may precede insulin resistance, diabetes mellitus, or vascular dysfunction at any age." (PMID 22254007, 2010). "Insulin resistance (IR) is the primary metabolic disorder associated with obesity and is defined as a diminished ability of insulin to stimulate glucose uptake by skeletal muscle and adipose tissue, in addition to reducing insulin's ability to suppress hepatic glucose production and output." (PMID 20529295, 2010). "The relationship between plasma levels of ET-1 and insulin (both endogenous and exogenous) is suggested by the fact that plasma levels of ET-1 are higher in patients with type 2 DM than in those with type 1 DM, most likely due to higher insulin levels and associated insulin resistance." (PMID 20664700, 2010). "However, chronic secretion of exogenous GH, even at a low level, may increase serum glucose and insulin levels in rats fed a standard diet, and thus increase the risk of insulin resistance." (PMID 20653983, 2010). "However, exogenous GH may also increase serum glucose and insulin levels in rats, and thus increase the risk of insulin resistance." (PMID 20653983, 2010).
Insulin resistance (continued). "Peripheral blood monocytes would encounter conditions of hyperinsulinemia and above normal concentrations of fatty acids in insulin resistant individuals; therefore, this metabolic situation may contribute the proinflammatory state that is associated with insulin resistance in vivo." (PMID 21054880, 2010). "Interestingly, in these experiments, inhibition of IL-6 signalling in obese mice increased hepatic insulin sensitivity, suggesting that IL-6 in an obese organism might cause insulin resistance." (PMID 21179199, 2010). "However, it has been demonstrated that insulin resistance associated with obesity largely stems from posttranslational modifications of insulin signaling proteins, such as inhibitory serine phosphorylation of the insulin receptor or its downstream signaling mediators." (PMID 20463885, 2010). "As skeletal muscle plays a major role in energy expenditure and insulin-stimulated glucose disposal, understanding changes that occur to this tissue with obesity and pre-diabetes development are critical to elucidating the underlying causes for insulin resistance and type 2 diabetes." (PMID 19806198, 2009). "Here we find in non-diabetic twins an association between SNPs and glucose uptake, whereas the T2D cases are characterized by a concert of different players where perhaps an insulin secretional defect may play the lead part and mask an association with insulin resistance." (PMID 19274082, 2009). "Insulin resistance is strongly associated with obesity, and one mechanism may be the generation of metabolic messengers such as free fatty acids by adipose tissue that inhibit insulin action on muscle." (PMID 18648539, 2008). "Interestingly, the variants in PPARG, ADIPOQ, and ENPP1, which elevate risk in obese populations, have been categorized as acting on insulin resistance while the TCF7L2 variant elevating risk in lean populations has been categorized as acting on insulin secretion." (PMID 18498634, 2008). "Given that these were young healthy subjects, matched for total body fat, VO2max and whole-body insulin sensitivity, we speculate that these are primary defects, likely to contribute to the pathogenesis of skeletal muscle loss and development of muscle insulin resistance associated with LBW." (PMID 19011679, 2008). "Although genetic mutations account for a minor role inthe large part of insulin resistance, an alteration of insulin signaltransduction, which may be due to genetic mutations, could contribute to theimpairment of insulin secretory profile and insulin resistance." (PMID 18604303, 2008). "The aim of this hypothesis is to discuss two complementary approaches to find out how high salt might interact with genetic defects along the insulin signaling and inflammatory pathways to predispose to insulin resistance in a genetically susceptible model of insulin resistance." (PMID 18570670, 2008). "The enlargement of adipocytes may not have pathophysiological significance by itself but rather be a manifestation of other pathogenetic factors leading to insulin resistance, such as increased adipocyte lipolysis resulting in elevated fatty acids, which in turn cause insulin resistance." (PMID 18320034, 2008). "The relationships between TNFα receptors and plasma lipids in the obese group disappeared after controlling for insulin sensitivity, suggesting that lipid abnormalities associated with TNFα system in obesity might be fully explained by TNFα-associated insulin resistance." (PMID 16803616, 2006). "Their association with birth weight may be explained by programming of metabolism due to undernutrition in utero, or by genetic factors: common genetic variants which increase insulin resistance may predispose both to low insulin-mediated growth in utero and insulin resistance in adulthood." (PMID 17125497, 2006). "Insulin resistance (IR) is characterized by impaired insulin signaling in skeletal muscle, liver, and adipose tissue." (PMID 42136573, 2026).